ENO1 (enolase 1)
Diseases named in the same sentence as ENO1 in open-access papers (continued):
Sharing a sentence is not in itself a finding about the gene and the disease.
cancer (continued). "Arginine residues 50 of ENO1 is methylated by protein arginine methyltransferase 5 (PRMT5) that plays an important role for increasing cell invasion and migration in cancer." (PMID 34671213, 2021). "In summary, we show that the well-established histological features of ccRCC, including lipid deposition and elevated expression of key cancer biomarkers (i.e., CA9 and ENO1), are significantly decreased with Ndufa4l2 knockdown in our TANdu mouse model." (PMID 34970493, 2021). "MSPA also inhibited cancer cell proliferation and induced apoptosis by inhibiting critical enzymes involved in the Warburg effect: aldolase A (ALDOA), enolase 1 (ENO1), and fumarate hydratase (FH)." (PMID 34681284, 2021). "Afterward, the catalytic activation of ENO1 was also enhanced via HIF, promoting survival of cancer cells in the hypoxia area by the modulating glycolytic metabolism." (PMID 34194464, 2021). "Alpha-enolase, also known as enolase-1 (ENO1), is a glycolytic enzyme that “moonlights” as a plasminogen receptor in the cell surface, particularly in tumors, contributing to cancer cell proliferation, migration, invasion, and metastasis." (PMID 33584813, 2020). "Our results showed that ENO1 expression was significantly higher in normal tissues as compared to KICH tissues, whereas high expression of ENO1 predicted poor OS in other cancers." (PMID 33643901, 2020). "Enolase 1 (ENO1) catalyzes the conversion of 2-phosphoglycerate to phosphoenolpyruvate and it is usually overexpressed in cancers, such as those in head and neck or lung." (PMID 32318352, 2020). "ENO1 depletion attenuates glycolysis, cell proliferation, EMT, migration, and invasion, and metastasis in several cancer types." (PMID 33584813, 2020). "ENO-1-dependent PLA formation allows pathogens as well as immune and cancer cells to invade tissue, consequently leading to infection, inflammation, and metastasis formation." (PMID 31106201, 2019). "Stimulation of macrophages with IFN-γ in combination with vitamin D3 as well as the treatment of cancer cells with CCL-2 or TNF-α enhanced ENO-1 transport to the cell surface." (PMID 31106201, 2019). "Another example is alpha-enolase (ENO1): ENO1 is upregulated by HIF under hypoxic conditions and has been shown to promote cell proliferation, cycle progression, cancer migration and invasion." (PMID 31198853, 2019). "The study provides solid evidence that there is the interaction between GRN A and ENO1 and the interaction is responsible for the effects of GRN A on glucose uptake as well as cancer cell migration and invasion." (PMID 28415822, 2017). "Our previous work demonstrated that ENO1 silencing increased reactive oxygen species (ROS) mainly generated through the sorbitol and NADPH oxidase pathways, which affect cancer cell growth and induce senescence." (PMID 28086938, 2017). "Alpha-enolase (ENO1), a major glycolytic enzyme, is reported to be over-expressed in various cancer tissues." (PMID 26882120, 2016). "In our previous studies, ENO1 was identified as a TAA in NSCLC patients, and the expression of ENO1 on the surface of cancer cells has been also described." (PMID 26551021, 2015). "Numerous extracellular proteins have been identified as plasminogen receptors, including ENO1, ANX2 and CK8, which are often de-regulated in cancer." (PMID 25860938, 2015). "For the first time, our paper describes EIF4A1, CLIC1, PRDX6, CLIC4, ENO1, ANXA4, EMD and Ku70 in relation to EEC, although their role is well established in other cancers." (PMID 22415234, 2012). "Three clear cell cancer lines (ES-2, TOV21G, and RMG1) were transfected with siRNA targeting HIF1 α (hypoxia) and ENO1 (glycolysis)." (PMID 21754983, 2011). "Notably, genes like fatty acid binding protein 5 (FABP5), enolase 1 (ENO1), phosphoglycerate kinase 1 (PGK1), and marker of proliferation Ki-67 (MKI67), which have been extensively studied in cancer biology, were included." (PMID 41328179, 2026).
cancer (continued). "We identified a robust upregulation of GLUT1 (SLC2A1), a key rate-limiting factor in the transport of glucose in cancer cells, and genes involved in central glucose metabolism (HK2, ENO1, PKM, and LDHA), PPP (G6PD), and de novo serine biosynthesis pathway (PSAT1, PSPH, and SHMT2)." (PMID 40371988, 2025). "ENO1 has been identified as a moonlight protein that plays critical noncanonical functions of metabolic enzymes in cancer." (PMID 40533767, 2025). "Enolase 1 (ENO1) is a conserved glycolytic enzyme that catalyzes the formation of phosphoenolpyruvate from 2-phosphoglycerate, an ATP-generating step that supports cancer cell proliferation and metastasis." (PMID 40821642, 2025). "The ELISA assay demonstrated that knockdown of ENO1 could decrease the SPP1 secretion of cancer cells, while overexpression of SPP1 in ENO1-KO cells could rescue it (Additional file3H, I)." (PMID 40665335, 2025). "Additionally, ENO1 influences the TME by modulating immune cell infiltration and promoting CD8+ T cell exhaustion in some cancers." (PMID 41373732, 2025). "For instance, in Glycolysis/ Gluconeogenesis and Biosynthesis of amino acids pathways, lysine 131 (K131) site of PGK1, K322 and K13 sites of ALDOA, K215 and K194 sites of GAPDH, K89 site of ENO1, K678 site of PFKM were hyper-lactylated in cancer cells and tissues." (PMID 40849487, 2025). "We first explored the effects of cancer cell proliferation with MET and anti-ENO1 antibody." (PMID 38515460, 2024). "The lack of circulating anti-ENO1 in healthy children compared to healthy adults suggests a more promising role for anti-ENO1 in paediatric cancer diagnosis." (PMID 38473245, 2024). "Notably, proteins enriched in CM included Moesin (MSN), Enolase 1 (ENO1), and polyA-binding protein 1 (PABPC1), which are considered tumorigenic in many types of cancer." (PMID 36923539, 2023). "TCM could inhibit cancer growth and metabolism by decreasing the expression level of glycolytic enzymes LDH, HKII and GLUT1, ENO1 in various cancers." (PMID 36732657, 2023). "ENO-1, which catalyzes the conversion of 2-phosphoglycerate to PEP and also acts as a plasminogen receptor and a DNA-binding protein, was shown to be overexpressed in several cancers." (PMID 36768924, 2023). "As for the GES-1 cells, differential ENO1 expression was detected in co-culture for 24 h but not 12 h or less, suggesting the cultured cancer cell AGS is more sensitive in ENO1 response to H. pylori infection than the normal cell GES-1." (PMID 36295613, 2022). "In addition to the expression level of cell surface-bound ENO-1, the amount of exosomal ENO-1 into the extracellular space was also correlated with the invasive metastatic potential of cancer cells." (PMID 34039961, 2021). "Altered energy metabolism in cancer cells is accompanied by the upregulation of several glycolytic enzymes, such as GLUT1, hexokinase 2, phosphofructokinase, enolase 1 (ENO1), aldolase A (ALDOA), lactate dehydrogenase A, and pyruvate dehydrogenase kinase, which stimulate the Warburg effect." (PMID 34681284, 2021). "Furthermore, ENO1 also displays multiple binding capacity to the DNA, mRNA 3, LncRNA and tRNA(CUU)Lys to regulate the gene transcription and translation in cancer cells 4,5." (PMID 34671213, 2021). "Whilst ENO1 is originally identified as a critical glycolytic enzyme whose expression is upregulated in malignant tumors, like many metabolic enzymes, ENO1 evolves other cellular functions independent of its glycolytic function." (PMID 34136381, 2021). "While, ENO1, like PKM2, promotes the Warburg effect, but also cancer invasion." (PMID 32183388, 2020). "ENO1 is a key glycolytic enzyme that catalyzes the production of phosphoenolpyruvate (PEP) from 2-phosphoglycerate (2-PG), which plays a crucial role in aerobic glycolysis and facilitates the Warburg effect in cancer cells 40-42." (PMID 32226539, 2020).
cancer (continued). "The expression of ENO1 in the other 16 cancer types was not significantly different from the respective controls (P > 0.01)." (PMID 33643901, 2020). "Our group and others identified citrullinated ENO1 in cancer cells, suggesting that this PTM could potentially trigger ENO1 autoantibodies in cancer patients." (PMID 33584813, 2020). "The ENOblock is a non-substrate cell permeable ENO-1 inhibitor that was originally discovered in a small molecule screening in cancer cell cytotoxicity assays." (PMID 31106201, 2019). "Given that SA and amoB1 inhibit ENO1 and PKM2 activity in vitro and SA suppresses aerobic glycolysis in vivo, our results raise the possibility that salicylates mediate their anti-cancer and anti-inflammatory effects, at least in part, by suppressing the Warburg effect." (PMID 31511554, 2019). "Interestingly, several well-known cancer biomarkers, THBS1, ENO1, and MUC1, were found to be expressed at much higher abundance in exosomes than total membrane proteins." (PMID 30646616, 2019). "The demonstration that SA and amoB1 bind and inhibit ENO1 and PKM2 in vitro, and that SA reduces the rate of aerobic glycolysis in HEK293 cells provides potentially useful insights into the anti-inflammatory and/or anti-cancer activities of salicylates." (PMID 31511554, 2019). "More specifically, genes ENO1, H3F3B and HSP90AA1 are important cancer drivers in human cells." (PMID 29882813, 2018). "It has been shown that enolase 1 (ENO1) may play an important role in tumorigenesis, cancer invasion, and metastasis." (PMID 29483925, 2018). "Interestingly, elements of Box B are known regulators of apoptosis in various contexts, including the neuronal environment with ENO1 and SLC16A4, and different types of cancer." (PMID 30157777, 2018). "In contrast, overexpression of ENO1 reversed the effect of GRN A on migration of cancer cells; the number of migrated cells was increased to 346 ± 46 in ENO1 transfected cancer cells treated with GRN A, compared with that (144 ± 21) in cells transfected with the control plasmid." (PMID 28415822, 2017). "We find that ENOblock does not inhibit Enolase in in-vitro enzymatic assays and that it does not show selective toxicity towards ENO1-deleted cancer cells." (PMID 28030597, 2016). "ENO1 silencing increased reactive oxygen species that were mainly generated through the sorbitol and NADPH oxidase pathways, as well as autophagy and catabolic pathway adaptations, which together affect cancer cell growth and induce senescence." (PMID 26734996, 2016). "To confirm that the metabolic adaptations observed after ENO1 silencing were not dependent on the exposure of the cells to high glucose concentrations, we mimicked physiological conditions by culturing cancer cells in low glucose medium." (PMID 26734996, 2016). "A significant increase in the level of anti-ENO1 Ab was observed in patients without cancer recurrence, while the anti-ENO1 Ab level was reduced in those with recurrence." (PMID 26551021, 2015). "ENO1, a glycolysis module protein, was overexpressed in HCC cells, and its increased level suggests that C. cicadae treatment increased the glycolytic activity of the cancer cells." (PMID 24872842, 2014). "Direct comparison of the cell surface proteins in super-invasive and non-invasive cancer cells revealed marked upregulation of numerous PLG-Rs including ENO-1, ANX2 and ACT in super-invasive cells, providing strong evidence for their involvement in cancer cell invasion." (PMID 25407528, 2014). "Mounting evidence showed ENO1 could partly inhibit the AMPK pathway in several cancers, but no related studies in GC (PAMC82)." (PMID 38515460, 2024). "Hence, the classification effectiveness of ten biomarkers which was assessed overall was based on GPX2 and GPX3 as factors from the enriched pathways and CAV1, ENO1, NQO1, and P4HB as factors from functional classes to determine whether a patient had cancer." (PMID 37955007, 2023).
cancer (continued). "ENO1, GAPDH, NQO1, PDIA4, and PDIA6 may serve as potential targets for cancer therapy." (PMID 37955007, 2023). "Furthermore, differential ENO1 expression was detected only between the cancer tissues and paracancerous tissues, but not between the H. pylori-positive cancer and the H. pylori-negative cancer specimens." (PMID 36295613, 2022). "The enzymes of glycolysis glyceraldehyde-3-phosphate dehydrogenase (GAPDH), enolase 1 (ENO1) and lactate dehydrogenase (LDHA) and glycerol-3-phosphate dehydrogenase (GPD1) which shuttles electrons to mitochondria, revealed a significant increase in carcinomas when compared to NAT." (PMID 35534478, 2022). "Furthermore, the expression of ENO1 and other glycolysis genes also can be regulated by sineoculis homeobox homolog 1 (SIX1), which interact with acetyltransferase 1 (HBO1) and Nuclear receptor coactivator 3 (AIB1) to affect Warburg effect in cancer." (PMID 34671213, 2021). "Altogether, the findings imply that MS13 may demonstrate its anti-cancer effects in U-87 MG and SH-SY5Y cells by downregulating GAPDH and ENO1, which disrupts the glycolytic pathway and subsequently results in the reduction of energy production and inhibition of cell proliferation." (PMID 33996900, 2021). "Interestingly, some studies reported that lncRNAs interact with ENO1 and affect its expression or activity, highlighting a novel approach to elucidate the non-metabolic roles of metabolic genes in cancer." (PMID 34627260, 2021). "Although the loss of ENO1 alone may not be lethal, cancer cells lacking ENO1 are selectively vulnerable to the loss of ENO2 (i.e. synthetic lethality), whereas non-cancer cells with intact ENO1 can tolerate a loss of ENO2." (PMID 24665131, 2014). "Besides, ENO1 is expressed on the surface of several cell types, where it acts as a plasminogen receptor, concentrating plasmin proteolytic activity on the cell surface, and thus ENO1 is involved in extracellular matrix (ECM) remodeling, cancer invasion, and metastasis by inducing angiogenesis." (PMID 37449059, 2023). "In addition, a series of enzymatic active inhibitors of ENO1, such as phosphonoacetohydroxamate acid (PhAH), (1,5-dihydroxy-2-oxopyrrolidin-3-yl)phosphonic acid (SF2312), deoxy-SF2312, Methyl-SF2312, POMSF, POMHEX and its derivatives, show potential anticancer in the functional cancer models 21,23." (PMID 34671213, 2021). "It is not known whether phosphorylation of ENO1 is related to cancer." (PMID 34332338, 2021). "However, the regulation of ENO1 in cancer cells is not clear." (PMID 28415822, 2017). "However, the molecular mechanisms of ENO1 favoring cancer angiogenesis have not yet been clear." (PMID 26882120, 2016). "Many other proteins thought to be highly abundant in EVs also did not have a pan-cancer expression, including GAPDH, HSPD1, and ENO1." (PMID 36470535, 2023). "This highlights a metabolic vulnerability of GB cells lacking ENO1, in which ENO2 deletion has inhibited the growth, survival and tumorigenic properties of cancer cells." (PMID 37298093, 2023). "In our study, we found that silencing NFATc2 in the EtOH-exposed OSCC cells resulted in a decrease in multiple genes involved in glycolysis and cancer stemness, including HIF1α, TP1, ENO1, PKM2, ALDH1A, Bmi1, and Oct4 (data not shown)." (PMID 36077186, 2022). "Quantitative real-time reverse transcription PCR (qRT-PCR) was used to measure the expression of ENO1 mRNA in 26 fresh primary NSCLC tissues (T), their corresponding para-cancer lung tissues (P), and their corresponding non-cancerous lung tissues (N)." (PMID 25887760, 2015). "Alpha-enolase (ENO1) is a multifunctional protein that is not only one of the enzymes involved in glycolysis, but also a fibrinogen receptor that promotes cancer metastasis." (PMID 30538002, 2018).
infection (23 papers, 2007 to 2025). The state of being infected such as from the introduction of a foreign agent such as serum, vaccine, antigenic substance or organism. "ENO-1 was found associated to BCVs in a BPE123-dependent manner at later times post-infection in BMDM." (PMID 27900285, 2016). "In addition, by using protein mutation and parasite infection rate analysis, it was demonstrated that ENO1 plays an important role in the C. parvum invasion of HCT-8 cells." (PMID 38504274, 2024). "Finally, we conducted proof-of-concept in vivo studies and showed that neutralization of cell surface Eno1 was effective for controlling C. albicans caused invasive infection." (PMID 33115324, 2020). "To further elucidate the biological significance of the ENO1–ACTB interaction during pathogen infection, we examined the changes in glucose, lactate, and ATP concentrations in cells following M. bovis infection." (PMID 40867552, 2025). "We observed that ENO1 gene expressed in HCT-8 cells was downregulated upon C. parvum infection at 3h which is the early stage of infection(P = 0.00169 < 0.01)." (PMID 38504274, 2024). "Antibodies to ENO1 consistently inhibited the parasite growth by ~ 40–50% in both 3 and 18 h infection assays with P values < 0.01." (PMID 38504274, 2024). "Our results showed that mild infection had higher antibody titer against with ENO1, in contrast to severe cases with low titer against ENO1." (PMID 35130884, 2022). "Our study applied a phenotypic intracellular library display system to identify anti-EV-A71 agent, and we have explored the role of ENO1 and anti-ENO1 antibody in EV-A71 infection." (PMID 35130884, 2022). "Collectively, through a promising intracellular scFv library expression and screening system, we found a potential scFv/antibody which targets host protein ENO1 and can interfere with the infection of EV-A71." (PMID 35130884, 2022). "Most importantly, however, the lack of enolase resulted in a significantly decreased infectivity of eno1/eno1 null mutant cells, compared to the wild type C. albicans strain SC5314 or eno1/eno1::ENO1 rescued cells in a mouse intravenous infection model." (PMID 32674422, 2020). "Extracellular RNA is released from injured cells during infection, it associates on the one hand with ENO present on bacteria and on the other hand with ENO-1 localized on eukaryotic cells thereby facilitating infection of lung epithelial cells." (PMID 31106201, 2019). "In vivo data suggests that ENO1 knockdown DCs lose the ability to induce a robust Th1 immune response that is required for infection clearance." (PMID 28525970, 2017). "In this context, it should be interesting to address the mechanism by which BPE123 affects the kinetic parameters of host ENO-1 and how this interaction modulates the outcome of the infection process." (PMID 27900285, 2016). "More interestingly, we demonstrated that ENO-1 catalytic activity is enhanced in THP-1 macrophages upon infection with B. abortus, with BPE123 playing a critical role in this phenomenon." (PMID 27900285, 2016). "Infection of CFPAC-1 cells with a second shRNA targeting the ENO1 CDS region (shENO1#2) gave similar results." (PMID 25860938, 2015). "Based on the importance of the glycolysis–HIF-1α–inflammation axis in infection and M. bovis’s reliance on glycolysis, this study specifically aimed to Identify and characterize the interaction between M. bovis ENO1 and host cell proteins, focusing on ACTB and its critical binding sites." (PMID 40867552, 2025). "To examine whether patient serum contain anti-ENO1 antibody, we found that mild infection cases contained higher anti-ENO1 titer than severe cases." (PMID 35130884, 2022). "In the present study, we first characterized that C. albicans cell wall-localized Eno1 could capture and “subvert” host plasminogen for facilitating invasive infection." (PMID 33115324, 2020).